VIM (vimentin)
Diseases named in the same sentence as VIM in open-access papers (continued):
Sharing a sentence is not in itself a finding about the gene and the disease.
cancer (continued). "The increasing of vimentin expression has been reported in diverse epithelial cancers, including breast cancer, prostate cancer, lung cancer, and other types of cancers." (PMID 28335269, 2016). "ZEB1 is an important regulator of EMT and is a target of miR-150; Vimentin and E-cadherin, widely used indicators of stromal invasion by cancer cells, are strongly up- and down-regulated, respectively, during EMT." (PMID 27566559, 2016). "For that reason of its over-expression in cancers and its role in mediating tumorigenic events, vimentin provide as an available targeted cancer therapy." (PMID 28335269, 2016). "They found that vimentin contributed to cytoskeleton organization and focal adhesion stability, which indicated that vimentin maintains cancer cell mechanical homeostasis." (PMID 27966589, 2016). "Upregulation of vimentin in cancers positively correlates with increased tumor invasion, growth and poor prognosis." (PMID 27322682, 2016). "Vimentin knockdown also reprograms cells to acquire cancer stem cell properties and induces a prolonged G2 arrest which contributes to drug resistance." (PMID 27322682, 2016). "Vimentin is a mesenchymal gene usually upregulated during epithelial-mesenchymal transition (EMT), a process associated with cancer CSCs/CS-LCs." (PMID 26880969, 2016). "EMT is a process that results in cancer cell migration, invasion, and metastasis with upregulation of vimentin]." (PMID 27363026, 2016). "In NSCLC, vimentin was involved in various aspects of cancer, including metastasis, drug resistance, EMT and recurrence." (PMID 27657690, 2016). "During EMT cancer cells partially downregulate EpCAM and epithelial features while gradually acquiring mesenchymal characteristics such as vimentin expression." (PMID 27391263, 2016). "In breast cancer, the downregulation of the epithelial marker E-cadherin and upregulation of the mesenchymal markers, N-cadherin and vimentin, were positively correlated with the high aggressiveness and rapid spread of cancer." (PMID 27661009, 2016). "Our results indicate that liprin-α1 localizes to different adhesion and cytoskeletal structures to regulate vimentin intermediate filament network, thereby altering the invasion and growth properties of the cancer cells." (PMID 27075696, 2016). "It has been reported that vimentin can also be expressed on the surfaces of various cancer cells and can be secreted under certain conditions on endothelial cells." (PMID 27713131, 2016). "Knockdown of Smad2/3 expression suppressed EGF-induced expressions of Snail, vimentin, fibronectin, and cancer cell invasion, suggesting an acquisition of the mesenchymal and migratory phenotype in less aggressive MCF-7 cells." (PMID 27829223, 2016). "Vimentin proteins have been implicated in many aspects of cancer initiation and progression, including tumorigenesis, EMT, and the metastatic spread of cancer." (PMID 27363026, 2016). "By mediating cytoskeletal organization and focal adhesion turnover, Vimentin was proved to contribute to mechanics of cancer cells in EMT." (PMID 27096955, 2016). "Transient knockdown of FASN suppressed hallmark structural and cytosolic/secretive proteins (vimentin, N-cadherin, fibronectin) in a model of EMT-induced cancer stem cells (CSC)." (PMID 27223424, 2016). "Vimentin, through its effects on cancer cellular morphology and cell signalling/gene expression cascades, likely integrates the process of EMT with the acquisition of resistance to butyrate and other HDACis." (PMID 27072512, 2016). "Vimentin is an intermediate filament that has been implicated in all EMT scenarios (embryonal development, tissue repair and cancer progression)." (PMID 26951092, 2016). "These markers were chosen, because both are known to change their expression level when cancer cells undergo EMT with an upregulation of vimentin and a downregulation of E-cadherin levels." (PMID 27553742, 2016).
cancer (continued). "The in vivo relevance is supported by the demonstration in the xenograft murine model that administration of 5-MTP reduces A549 cancer cell vimentin expression." (PMID 27145282, 2016). "During EMT, cancer cells switch off the expression of epithelial markers such as E-cadherin and turn on the expression of mesenchymal markers such as vimentin." (PMID 27013588, 2016). "It has been well accepted that down-regulated E-cadherin and up-regulated vimentin expression in the EMT process are unique features of the metastatic property in cancer cells." (PMID 28033430, 2016). "Some anti-cancer drugs that are currently used in the clinic directly target vimentin such as “silibinin”33 and “withaferin A”34." (PMID 26932781, 2016). "These liposomes have shown higher cancer cell cytotoxicity effects triggered by gal- doxorubicin/vimentin siRNA liposome (Gal-DOX/siRNA-L) than each single treatment." (PMID 28335269, 2016). "Recently, increasing evidence has demonstrated that vimentin exerted a substantial influence on the progression and prognosis of cancer." (PMID 27657690, 2016). "Our findings that 5-MTP administration suppresses vimentin expression in A549 xenograft cancer cells are consistent with the notion that 5-MTP exerts its anti-cancer actions by inhibiting NF-κB activation." (PMID 27145282, 2016). "In both the control SKOV3/pcDNA and the SKOV3/TTP cells, these mRNAs were stable for 6 h after actinomycin D treatment, indicating that TTP does not directly affect the expression of the EMT markers E-cadherin, N-cadherin, or vimentin in cancer cells." (PMID 26840564, 2016). "Based on these findings and previous reports indicating that the collapse of vimentin filaments inhibits cancer progression, we concluded that restoring ITSN-1s protein level stabilizes the cells and contributes to decreased motility and metastasis." (PMID 27629044, 2016). "Analysis of pull-down products by mass spectrometry (MS) revealed that the DEspR-protein interacts with several proteins involved in intracellular trafficking, angiogenesis, and/or cancer: vimentin, Gal-3, Gal-1 and TMED10." (PMID 27301377, 2016). "Vimentin expression in the cancer tissues was stained by IHC and expression level was determined by measuring vimentin positive area under imaging analysis." (PMID 27145282, 2016). "Vimentin expression at the cancer invasive front was detected in 35.3% (49/139) of samples from patients with ESCC." (PMID 26095281, 2015). "The expression of vimentin leads cancer cells more sensitive to WFA treatment, which induces cell apoptosis." (PMID 25965826, 2015). "By using a treatment of Withaferin-A (WFA) (i.e., a bioactive compound with anticancer properties), cancer malignancy is substantially reduced in vimentin-expressing cancer cells." (PMID 25965826, 2015). "Vimentin contributed to cytoskeleton organization and focal adhesion stability, which indicated that vimentin maintains cancer cell mechanical homeostasis." (PMID 25965826, 2015). "This EMT program displayed a significant reduction of E-cadherin and occludin expression, and a marked increase of N-cadherin, vimentin, and nuclear β-catenin expression, resulting in cancer cells evolving into a highly invasive and mesenchymal phenotype." (PMID 25645291, 2015). "Increased expression of mesenchymal markers, e.g., N-cadherin, vimentin and fibronectin, contributes to the enhanced motility of cancer cells." (PMID 26131016, 2015). "Vimentin expression is commonly up-regulated upon cell “activation” in such contexts as regeneration, wound repair and cancer, and in activated macrophages and glia." (PMID 26041885, 2015). "In prostate tumors, both silibinin and flavonolignan inhibited invasion, motility, and migration of the cancer cells via downregulation of vimentin in cancer cell lines and mice models." (PMID 26425122, 2015). "The NF-κB transcription factor is associated with cancer metastasis by modulating EMT related factors including E-cadherin, MMP and Vimentin." (PMID 25996501, 2015).
cancer (continued). "Vimentin is often upregulated during cancer progression and plays a key role in the epithelial to mesenchymal transition and cell invasion." (PMID 25831049, 2015). "We observed an apparent increase in vimentin in the intersection area between cancer cells and fibroblasts for both transfected cells." (PMID 25887999, 2015). "In vimentin depleted cancer cells, the cell malignancy was reduced and the mechanical strength was impaired." (PMID 25965826, 2015). "The cancer cells assume fibroblast characteristics such as increased migration; and expression of mesenchymal markers Vimentin, Snail-1 and Zeb; and decrease expression of epithelial markers in the cancer cells." (PMID 26029109, 2015). "On the other hand, the decreased cancer cell motility upon miR-622 overexpression was restored upon transfection of A549 cells with an inhibitor against miR-622, and vimentin level was restored to that of the control." (PMID 26528854, 2015). "Cytokeratin 19 and vimentin expression was analysed in the carcinomas in order to evaluate if injected cancer cells can give rise to distinct cell types." (PMID 25885700, 2015). "Since EMT is an important driver in cancer invasion, we studied the expression of vimentin and snail/slug in invasive areas of SCC." (PMID 26594799, 2015). "Though vimentin expression is found in later cancer stages and correlates to malignancy, the role of vimentin in the regulation of cancer malignancy is unclear." (PMID 25965826, 2015). "Through the application of small interfere (si) and small hairpin (sh)-RNA in MDA-MB 231 cells, we were able to knock down vimentin and investigated its functional role in cell mechanics and cancer progression." (PMID 25965826, 2015). "In the metastasis of cancer, the increased motility and invasive behavior of cancer cells underwent EMT, due to the loss of adhesion molecules such as E-cadherin, and the gain of mesenchymal proteins such as N-cadherin and vimentin." (PMID 26580601, 2015). "The emerging relevance of vimentin in tumor progression turns it into an attractive target for cancer therapy." (PMID 26292717, 2015). "It is reported that many cancer cells exhibit decreased expression of E-cadherin and increased expression of N-cadherin and vimentin, which are significantly correlated with the malignant degree of cancers and the metastasis of cancers to the lymph nodes." (PMID 26702618, 2015). "Vimentin also mediated cytoskeleton architecture by orienting microtubules and actin fibers, stabilizing focal adhesions, and then resulted in cancer cell force generation, migration, and malignancy." (PMID 25965826, 2015). "The presence of vimentin on the surface of cancer cells is considered a sign of a mesenchymal phenotype of CTCs." (PMID 26167450, 2015). "In the current study, our results revealed the role of vimentin in EMT-related cancer mechanotransduction." (PMID 25965826, 2015). "Vimentin was also included as a test for evidence of EMT, which has been implicated in many aspects of cancer progression and cancer initiation." (PMID 26040322, 2015). "Epithelial-mesenchymal transition (EMT), during which cancer cells lose epithelial markers such as E-cadherin but gain mesenchymal markers such as vimentin, is known to be deeply involved in cancer progression and chemotherapy resistance." (PMID 26203858, 2015). "Markedly, the positivity of CK decreased according to grade of TCC whereas vimentin increases according to the grade of the carcinoma." (PMID 26640315, 2015). "SNAI1 has also been reported to increase the expression of mesenchymal markers Vimentin and Fibronectin as well as other proteins involved in cancer invasion such as metalloproteinases 2 and 9, and various transcription factors such as ZEB-1 and LEF-1." (PMID 24565133, 2014). "Vimentin is another key molecule that is frequently altered in cancer cells, and is responsible for cell anchorage and regulation of organelle position within the cytosol." (PMID 24949273, 2014).
cancer (continued). "It is reported that ZEB2 is a vital EMT inducer through suppressing E-cadherin or inducing vimentin expression in human cancer." (PMID 24626466, 2014). "Since EMT has been linked to cancer stem cells, we set out to study the EMT markers E-cadherin and vimentin in this context." (PMID 25238228, 2014). "Serial frozen sections that utilized the cancer cell markers vimentin or CK19 confirm that the dextran freely diffused throughout and around the claudin-low tumors but was largely restricted to the vasculature in luminal tumors." (PMID 23975155, 2014). "E-cadherin was mainly confined to cell membranes, while Snail was observed in nuclei of cancer cells, and vimentin was expressed in the cytoplasm." (PMID 24945379, 2014). "Following vimentin-positive droplet sorting and downstream analysis of recovered nucleic acids, we found that cancer-specific genomes and transcripts were significantly enriched." (PMID 25030902, 2014). "EMT is crucial for cancer cells to acquire invasive phenotypes, which are characterized by downregulation of E-cadherin and upregulation of vimentin." (PMID 25107280, 2014). "There are reports that E-cadherin and Vimentin can be regulated via DNA methylation in various cancer entities." (PMID 24959847, 2014). "Studies of human epithelial carcinoma cell lines have demonstrated that Vimentin expression was induced in invasive cell lines, we also found Vimentin protein level was decreased in CS-inhibited cancer cells (P<0.05)." (PMID 25545012, 2014). "Signaling by extracellular matrix MMPs, cell surface sialoglycoprotein podoplanin, intracellular small GTP-binding p21Rac1, and vimentin proteins are well known to regulate processes of cellular motility, migration and invasion of cancer cells." (PMID 24598827, 2014). "Vimentin is an intermediate filament protein known to participate in epithelial-to-mesenchymal transitions and can serve as a biomarker for some cancer cell types." (PMID 25030902, 2014). "Elevated vimentin expression levels correlate well with upregulated migration and invasion of cancer cells." (PMID 24527079, 2014). "Vimentin is transcriptionally silent in normal epithelia and aberrant vimentin expression has been used as a cancer marker in fecal DNA testing." (PMID 24748968, 2014). "It has previously been demonstrated that vimentin expression is substantially increased in cancer cells of hepatic metastasis." (PMID 25949790, 2014). "Hyperactivation of FAK has been reported in cancer cell lines and cancer metastasis, and Src-mediated regulation of E-cadherin and vimentin has also been reported in several cancers." (PMID 25337707, 2014). "During EMT, cancer cells lose E-cadherin-mediated cell-cell adhesion and acquire characteristics of mesenchymal cells, including the expression of vimentin." (PMID 25120667, 2014). "EMT is closely correlated with the invasion of cancer cells, through which the expression of E-cadherin and Vimentin will change." (PMID 25244643, 2014). "The contribution of cancer cells in the MPP component to adenocarcinoma lymphatic invasion was assessed using vimentin as a marker." (PMID 25120667, 2014). "It was also analysed the expression level of N-cadherin and vimentin mesenchymal markers, which are frequently expressed in carcinoma cells that have undergone EMT." (PMID 25012153, 2014). "ix) Finally, localization of CD68+ (H2) and CD163+ (I2) macrophages close to carcinoma cells as well as high expression of FoxP3 (O2), L1CAM (P3) and vimentin (R), respectively, tended to be associated with higher grading (S)." (PMID 24797069, 2014). "On the other hand, the mesenchymal intermediate filament, vimentin, often increases its expression in carcinoma cells that have undergone an EMT." (PMID 25012153, 2014). "Vimentin immunoactivity was observed in 14 carcinoma tissues where AQP3 was overexpressed and E-cadherin was lacking." (PMID 24887009, 2014).
cancer (continued). "This study identifies WIPF2, EPHB4 and MTHFD2 as novel regulators of vimentin expression by using a high-throughput RNAi screening approach targeting cancer relevant genes." (PMID 23295955, 2013). "We found that all of the COVCAR cell lines and NOSE cells expressed cytokeratin and vimentin as in human cancer cell lines and OSE cells." (PMID 23460878, 2013). "While loss of E-cadherin causes dysfunction of the cell-cell junction system, thus triggering cancer cell invasion and metastasis, vimentin is a ubiquitous mesenchymal intermediate filament supporting mechano-structural integrity of quiescent cells." (PMID 24392029, 2013). "Last but not least, here we present preliminary morphological evidence for the possible role of vimentin in depolyploidization of giant cancer cells appearing as a result of a pre-senescent stage induction." (PMID 23383739, 2013). "Vimentin existed in mesenchymal cells and was a marker commonly used to identify cancer cells in the EMT process." (PMID 23977005, 2013). "Despite the important role of vimentin in cancer cell behavior, relatively little is known about its regulation." (PMID 23295955, 2013). "In some cell types, down-regulation of vimentin has been proposed to inhibit apoptosis, contributing to cell survival and resistance to various anti-cancer agents." (PMID 24019887, 2013). "We investigated expression of the EMT-related molecules E-cadherin, N-cadherin and vimentin in cancer cells following treatment with AR-A04418 and GSK3β-specific siRNA." (PMID 23408967, 2013). "Since vimentin has such an important role in regulating cancer cell migration and invasion, it has been suggested as a potential target for cancer therapy." (PMID 23295955, 2013). "Vimentin is abundantly expressed by mesenchymal cells and plays a critical role in wound healing, angiogenesis and cancer growth." (PMID 23785295, 2013). "The loss of epithelial features is accompanied by increased motility, resistance to anti-cancer drugs, and expression of mesenchymal genes such as vimentin and N-cadherin." (PMID 23426189, 2013). "The functions of NF-κB in the transcription of the mesenchymal genes encoding VEGF, Vimentin, MMP-2 and MMP-9 are critical for promoting and maintaining a mesenchymal phenotype in cancers." (PMID 22640183, 2012). "IHC analysis with E-cadherin or vimentin disclosed different expression patterns in cancer and normal sites." (PMID 22963683, 2012). "Integrin β 4 and vimentin are cleaved by caspase 3 and 7 in apoptosis, which have been recognized as potential molecular targets for cancer treatment." (PMID 23211466, 2012). "Studies have shown that VIM functions in cell adhesion, migration, survival, and cell signaling processes via dynamic assembly/disassembly in cancer cells." (PMID 22766839, 2012). "High expression of E-cadherin was observed in As1/Sic50 and As1/Sic54 tumors, while high expression of vimentin was observed in cancer cells of As1/Mock3 tumors." (PMID 22844455, 2012). "Up-regulated proteins in each model included 14-3-3 protein theta and alpha enolase from HOS/143B, and nestin and vimentin from SaOS-2/LM7, all of which have been implicated in cancer progression and metastasis." (PMID 22640921, 2012). "Specifically, E-cadherin was expressed at the normal site in each tissue (lung and intestine), while vimentin was expressed at the cancer site in each tissue, especially in the intestine, where expression was detected in the lesion center." (PMID 22963683, 2012). "Recent studies showed that VIM functions in cell adhesion, migration, survival and cell signaling processes via dynamic assembly/disassembly in cancer cells." (PMID 22766839, 2012). "A number of studies have described protumorigenic and prometastatic properties of vimentin-expressing cancer cells, and vimentin expression has been found to correlate with poor outcome in many cancers." (PMID 22912669, 2012).